MST1 (macrophage stimulating 1)
Diseases named in the same sentence as MST1 in open-access papers (continued):
Sharing a sentence is not in itself a finding about the gene and the disease.
infarction (4 papers, 2016 to 2022). A localised pathological necrosis of tissue resulting from obstruction of the blood supply usually by a thrombus, an embolus, or vascular torsion. "Mst1 has also been reported to promote cardiac fibrosis and cardiomyocyte death in cases of post-infarction cardiac injury." (PMID 29760744, 2018). "Our results identify Mst1 as a malefactor in the development of post-infarction cardiac injury and that it acts through the JNK-Drp1-mitochondrial fission pathway." (PMID 29760744, 2018). "Mammalian STE20-like kinase 1 (Mst1), a regulator of cellular apoptosis, is involved in cardiac remodeling in post-infarction heart, but the mechanisms remain poorly defined." (PMID 29760744, 2018). "Our study also found that Mst1 expression was much higher in the myocardium post-MI and that this contributed to post-infarction cardiac injury through the promotion of cardiomyocyte mitochondrial apoptosis." (PMID 29760744, 2018). "More importantly, there is an incomplete understanding of whether Mst1 acts via regulation of mitochondrial homeostasis in post-infarction cardiac injury." (PMID 29760744, 2018).
influenza (4 papers, 2012 to 2024). An acute viral infection of the respiratory tract, occurring in isolated cases, in epidemics, or in pandemics; it is caused by serologically different strains of viruses (influenzaviruses) designated A, B, and C, has a 3-day incubation period, and usually lasts for 3 to 10 days. "In this study, MST1 and PRSS12 were implicated in CRE/CREB signaling; however, in response to influenza infection, CRE signaling levels in cells treated with siPRSS12 were unchanged compared to both pathway reporter and siNEG controls." (PMID 22606348, 2012).
neutropenia (4 papers, 2013 to 2022). A decrease in the number of neutrophils found in the blood. "Autoimmunity may be a feature of both MST1 deficiency and WAS, in particular autoimmune haemolytic anaemia, thrombocytopenia and neutropenia." (PMID 26801501, 2016).
non-small cell lung carcinoma (4 papers, 2014 to 2022). A group of at least three distinct histological types of lung cancer, including non-small cell squamous cell carcinoma, adenocarcinoma, and large cell carcinoma. "For example, overexpression of Mst1 in non-small-cell lung cancer (NSCLC) cells inhibits cellular proliferation and survival through YAP phosphorylation." (PMID 25097728, 2014).
primary sclerosing cholangitis (4 papers, 2018 to 2024). "The macrophage stimulating 1 (MST1) gene is critical in the regulation of the Hippo signaling pathway, encoding the receptor kinase RON ligand macrophage-stimulating protein (MSP, also known as MST1), and is associated with the pathogenesis of primary sclerosing cholangitis (PSC)." (PMID 36497451, 2022).
sarcoma (4 papers, 2018 to 2021). A usually aggressive malignant neoplasm of the soft tissue or bone. "By immunohistochemistry, TAZ/YAP activated clinical sarcoma samples demonstrated loss of MST1 (47%), MST2 (26%), LATS1 (19%), and LATS2 (27%)." (PMID 30167083, 2018). "qRT-PCR in sarcoma cell lines demonstrated loss of expression of the Hippo kinases at the RNA level, most pronounced in MST1 (42%) and MST2 (25%)." (PMID 30167083, 2018). "Within these TAZ/YAP activated sarcomas, 47% (54/114) demonstrated loss of MST1 expression, 26% (30/117) demonstrated loss of MST2 expression, 19% (22/113) of the sarcomas demonstrated loss of LATS1 expression, and 27% (32/117) of the sarcomas demonstrated loss of LATS2 expression." (PMID 30167083, 2018). "Studies show that promoter methylation of Lats1 and Lats2 is common in schwannomas (17% and 30%, respectively), while promoter methylation of Mst1 and Mst2 has been detected in 37% and 17% of sarcomas, respectively." (PMID 32960816, 2020). "Seven of the 12 sarcoma cell lines (58%) demonstrated a two-fold or greater increase in expression of MST1 with treatment with TSA." (PMID 30167083, 2018). "Approximately 49% of sarcomas (73/148) demonstrate loss of MST1, 31% of sarcomas (46/148) demonstrate loss of MST2, 23% of sarcomas (34/148) demonstrate loss of LATS1 expression, and 29% of sarcomas (45/153) demonstrate loss of LATS2." (PMID 30167083, 2018). "Loss of expression of MST1 and MST2 was identified in 15% (17/114) of sarcomas." (PMID 30167083, 2018). "Loss of expression of the Hippo kinases was identified in clinical sarcoma samples demonstrating activated TAZ and YAP at a relatively high level, ranging from 19% (LATS1) to 47% (MST1)." (PMID 30167083, 2018). "Still, compared to its scatter-factor relative MET, RON and its unique ligand MSP (macrophage stimulating protein; also known as macrophage stimulating 1) remain understudied and have not been investigated in sarcomas." (PMID 32272784, 2020).
Sepsis (4 papers, 2023 to 2025). Sepsis is defined as life-threatening organ dysfunction caused by a dysregulated host response to infection. "Specifically, MST1/2-deficient mice exhibited increased susceptibility to CLP-induced sepsis." (PMID 40825908, 2025). "Studies have reported that lipopolysaccharide (LPS) can promote Drp1 expression in sepsis models by up-regulating Mammalian STE20-like kinase 1 (Mst1), activating mitochondrial fission, and enhancing mitochondria-related apoptotic signaling." (PMID 40041174, 2025). "Furthermore, coordinated with melatonin, Irisin could protect the heart against sepsis-induced myocardial depression via impeding the macrophage stimulating 1 (Mst1) and hence JNK pathway." (PMID 37047523, 2023).
ankylosing spondylitis (3 papers, 2022 to 2024). An autoimmune chronic inflammatory disorder characterized by inflammation in the vertebral joints of the spine and sacroiliac joints. "Analyses of MST1 beyond rs3197999 link it also to other diseases, which is illustrated by MST1 rs9858542—a risk factor for both CD (more frequent homozygosity of the minor allele) and ankylosing spondylitis (more frequent heterozygous genotype, compared with controls)." (PMID 39202524, 2024).
Arthritis (3 papers, 2014 to 2018). Inflammation of a joint. "In contrast, μCT analysis of the affected joints revealed only minor arthritis-associated degenerative changes in Mst1−/− mice." (PMID 24852423, 2014). "Moreover, Mst1 deficiency significantly reduced histological signs of arthritis, including synovial inflammation and cartilage/bone destruction." (PMID 24852423, 2014). "Further differences in the severity of arthritis between Mst1−/− and WT mice were revealed by three-dimensional X-ray tomography (μCT)." (PMID 24852423, 2014).
cognitive decline (3 papers, 2022 to 2025). "Mapping of GWAS results identified genes that have been previously associated with cognitive decline including STAU1, SEMF3A, IP6K1, MST1, the ATNX2/BRAP locus, ALDH2 and DDX27, where a likely functional missense variant is highly associated." (PMID 35052462, 2022). "Interestingly, it has been shown that Mst1 overexpression can induce cognitive decline and synaptic dysfunctions in an Alzheimer's mouse model." (PMID 40439020, 2025).
Cognitive impairment (3 papers, 2025 to 2026). Abnormal cognition is characterized by deficits in thinking, reasoning, or remembering. "Knocking down MST1 in hippocampal and cortical tissues of 5xFAD mice improved cognitive deficits, reduced p-tau protein levels, and alleviated neurodegeneration and neuroinflammatory responses." (PMID 41689046, 2026). "Likewise, in the 5xFAD mouse model, MST1 overexpression leads to earlier onset of cognitive deficits and AD pathology." (PMID 41013661, 2025). "In APP/PS1 mice, XMU-MP-1 administration protects against cognitive deficits and reverses signs of astrocytic senescence through a mechanism requiring YAP, demonstrating that MST1 inhibition is also beneficial in non-neuronal brain cell types." (PMID 41013661, 2025).
colitis (3 papers, 2013 to 2023). Inflammation of the colon. "To determine whether the Mst1 deficiency altered Foxp3+ Treg cell functions, we employed the experimental colitis model induced by adoptive transfer of naïve T cells into Rag2-/- mice." (PMID 24040101, 2013). "Consistent with the dysfunction of Mst1−/− Treg, Mst1−/− Treg cannot suppress colitis induced by the adoptive transfer of CD62Lhi naïve T cells into healthy mice." (PMID 29459865, 2018). "We found that Mst1 is required for the suppression of T cell–induced colitis and T cell proliferation in vitro by natural Foxp3+ CD4+ Treg cells." (PMID 24040101, 2013). "These combined defects likely explain the severe impairments of Mst1-/- Treg cells in the suppression of experimental colitis." (PMID 24040101, 2013). "Since Mst1 is required for lymphocyte trafficking, the diminished ability of Mst1-/- Treg cells to suppress experimental colitis may be due to the impaired trafficking of Mst1-/- Treg cells." (PMID 24040101, 2013). "In contrast, Mst1-/- Foxp3+ Treg cells were not able to prevent colitis and showed a similar degree of the body weight loss as mice that received only naïve T cells." (PMID 24040101, 2013). "Since Mst1 also regulates interstitial migration, the combined effects of impaired motility and IS formation may aggravate in vivo Treg suppression, as seen in the experimental colitis model." (PMID 24040101, 2013). "Mst1-/- Treg cells failed to prevent the development of experimental colitis and antigen-specific suppression of naïve T cells proliferation in vitro." (PMID 24040101, 2013). "Here we showed that Mst1-/- Treg cells failed to prevent the development of experimental colitis and antigen-specific suppression of naïve T cells proliferation in vitro." (PMID 24040101, 2013).
E. coli infection (3 papers, 2019 to 2024). "Interestingly, loss of Mst1/2 or Mst1/2 kinases inhibitor treatment abrogated filopodia formation or actin accumulation at sites of bacteria induced by LPS or the Piezo1 agonist Yoda1 treatment or E. coli infection." (PMID 34112781, 2021). "Expression of MST1 was sufficient to suppress E. coli infection." (PMID 38624208, 2024). "Consistently, with SIM approach, Mst1 protein was condensed and formed large aggregates after E. coli infection (from 5 min and at least last for 60 min), and Keap1 co-localized with Mst1 after E. coli infection at 5/15/30 min time points, but not at 60 min in BMDM." (PMID 30765703, 2019).
esophageal cancer (3 papers, 2016 to 2025). A primary or metastatic malignant neoplasm involving the esophagus. "Our results showed that the core components of the Hippo pathway (Mst1/2, LATS1, and Mob1) and the RASSF1 protein coimmunoprecipitated and that their binding was significantly enhanced by rhBMP-2 treatment in both esophageal cancer cell lines." (PMID 27230238, 2016).
fibrosis (3 papers, 2016 to 2022). the formation of excess fibrous connective tissue in an organ or tissue in a reparative or reactive process. "Consistent with augmented cardiac fibrosis and collagen expression in MST‐1 mice, expression of cardiac BNP and β‐MHC was also greater in this genotype compared to WT mice (P ≤ 0.03)." (PMID 27081162, 2016).
fungal infections (3 papers, 2012 to 2018). "A genetic approach was employed to selectively delete MST1 in DC cells and results showed that loss of MST1 in DCs causes massive inflammation in multiple tissues in old-aged mice and promotes Th17 cell differentiation in autoimmune or fungal infection inflammation." (PMID 28145433, 2017). "We report here the whole-exome based discovery of AR MST1 deficiency in a 19-year-old patient with a T-cell deficiency associated with EV-HPV, bacterial and fungal infections." (PMID 22952854, 2012). "The present study shows that an integrated MST1–p38MAPK–MK2/MSK1–CREB signalling axis in DCs directs the generation of the Th17 subset in both autoimmune and fungal infection inflammation." (PMID 28145433, 2017). "Nine days after infection, Mst1ΔDC mice displayed significantly attenuated pathological kidney injuries, less fungal survival in the kidney and higher serum IL-17 production, but not IFNγ production, indicating that MST1 signalling is required for precipitating the fungal infection in DCs." (PMID 28145433, 2017).
glioblastoma (3 papers, 2016 to 2019). The most malignant astrocytic tumor (WHO grade IV). "In response to apoptotic stimuli, hMOB3s bind to MST1 through conserved positively charged residues, thereby negatively regulating apoptotic MST1 signalling in glioblastoma multiforme cells by inhibiting the MST1 cleavage-based activation process." (PMID 31185650, 2019). "Recently, a study found that miR-130b, situated upstream of MST1/2-Lats-YAP/TAZ, was substantially overexpressed in human glioblastoma growth." (PMID 29896440, 2018).
Hypertension (3 papers, 2019 to 2026). The presence of chronic increased pressure in the systemic arterial system. "Therefore, melatonin can recover the decreased mitochondrial membrane potential induced by hypertension and Mst1 over-expression." (PMID 37005605, 2023). "Hence, melatonin can significantly inhibit the increase of MDA and the decrease of SOD and GSH-PX activity induced by hypertension and Mst1 over-expression." (PMID 37005605, 2023). "Interestingly, cardiac‐specific Mst1 knockout failed to reduce Ang II‐induced hypertension, which signifies that the role and mechanisms of Mst1‐specific deletion alleviating Ang II‐induced cardiomyocyte apoptosis were independent of the reduction of arterial pressure." (PMID 30338935, 2019).
Infertility (3 papers, 2021 to 2023). "Since db/db and ob/ob mice are infertile, genetically engineered mouse models with simultaneous mutations in Mst1 and the leptin receptor are poorly accessible, while STZ-induced DCM models are widely used." (PMID 33953853, 2021). "More than that, according to String analysis, Mug1, Pzp, Cst3, Ctsb, and Mst1 were involved in female pregnancy, and their downregulation might be the cause of infertility and poor reproductive outcomes in female patients with hyperthyroidism." (PMID 35720307, 2022).
liver fibrosis (3 papers, 2018 to 2024). "In the present study, we found that MST1 protects against liver fibrosis caused by Schistosoma infection." (PMID 39700261, 2024). "Overall, our data identified MST1 as a novel regulator for egg-induced liver fibrosis via modulation of macrophage function and phenotype by CD36-mediated phagocytosis and suppression of NF-κB pathway." (PMID 39700261, 2024). "Mst1flox/flox (also called Mst1+/+ or WT mice here) and Mst1△M/△M mice were infected percutaneously with 20 ± 5 cercariae to constructed S. japonicum-induced liver fibrosis model as previously reported." (PMID 39700261, 2024). "In a murine model of schistosomal infection, we observed a pronounced exacerbation of liver fibrosis in mice with macrophages specific Mst1 knockout." (PMID 39700261, 2024). "Our study, aligning with previous research, shows that MST1 knockout intensifies liver fibrosis by enhancing TH17 and Th2 responses." (PMID 39700261, 2024). "In this study, we reveal a previously undiscovered function of MST1: that of the protective role of MST1 in schistosomiasis-induced liver fibrosis." (PMID 39700261, 2024). "Altogether, our data has identified MST1 as a novel regulator for egg-induced liver fibrosis via modulation of macrophage function and phenotype." (PMID 39700261, 2024). "Collectively, S. japonicum-infected mice model demonstrates the protective role of MST1 in macrophages during egg-induced liver fibrosis." (PMID 39700261, 2024). "In a murine model of schistosomal infection, we observed a pronounced exacerbation of liver fibrosis in animals with a targeted Mst1 gene deletion in macrophages." (PMID 39700261, 2024). "Previous studies have shown that CTGF is associated with inflammation, pathogenesis and progression of hepatic fibrosis, in the Hippo signaling pathway and inhibition of MST1/2 signaling." (PMID 29495545, 2018). "However, the effects of MST1 on the phenotype of macrophages in schistosomiasis-induced liver fibrosis are still unclear." (PMID 39700261, 2024). "This suggests that the enhancement of MST1 activity could potentially offer therapeutic benefits for liver fibrosis." (PMID 39700261, 2024). "To investigate whether MST1 plays a direct role in egg-induced liver fibrosis, we produced myeloid (including macrophages) specific Mst1 knockout mice (termed Mst1△M/△M mice) by crossing Mst1flox/flox mice with LysMCre mice." (PMID 39700261, 2024). "While our study primarily focused on the impact of MST1 on macrophage polarization and liver fibrosis, it is possible that MST2 may also potentially influence these processes through similar or distinct mechanisms." (PMID 39700261, 2024). "These in vivo and in vitro data show that S. japonicum infection downregulates the expression of MST1 in macrophages, suggesting MST1 may play a regulatory role in schistosomiasis-induced liver fibrosis." (PMID 39700261, 2024). "Our study revealed that mice lacking MST1 specifically in macrophages exhibited more severe liver fibrosis when infected with S. japonicum." (PMID 39700261, 2024). "We wondered whether MST1 is downregulated post schistosome infection because SEA acts through TLR2/4 signaling and is important in Schistosoma egg-induced liver fibrosis." (PMID 39700261, 2024). "Furthermore, EMPA successively induced the phosphorylation of MST1/2 and YAP, the two central members of the Hippo signalling pathway, in the CDAHFD-induced liver fibrosis model." (PMID 35625768, 2022). "However, the specific role of MST1 in Schistosoma-induced liver fibrosis has not been fully understood." (PMID 39700261, 2024).
memory impairment (3 papers, 2022 to 2025). "The reduction in MST1 activity inhibiting Foxo3a activation might be linked to abnormal neural activity patterns and memory impairment." (PMID 39413003, 2025). "Mst1-overexpression may induce memory impairments via disturbing the patterns of neural activities, which is possibly associated with the abnormal GABAergic expression level." (PMID 35656451, 2022). "In addition to this, various proteins of the Hippo signaling pathway are linked via Wnt-signaling and other pathways to stress-regulated signaling cascades, while overexpression of MST1 induces memory impairment via disturbances in the patterns of neural activities." (PMID 37658054, 2023).
pancreatitis (3 papers, 2018 to 2024). Inflammation of the pancreas. "First, deleting Mst1&2 with an inducible acinar cell-specific Cre or overexpressing YAP1 in the pancreas reproduced the Mst1&2 whole pancreas epithelial knockout phenotype – acinar atrophy, ductal expansion, and pancreatitis-like phenotype." (PMID 39051998, 2024). "The knockout mice displayed a very severe pancreatitis-like phenotype, which differs from the phenotype seen in both Mst1/2 knockout studies." (PMID 34079799, 2021).